NOTCH1 (notch receptor 1)
Diseases named in the same sentence as NOTCH1 in open-access papers (continued):
Sharing a sentence is not in itself a finding about the gene and the disease.
T-cell leukemia (35 papers, 2009 to 2024). A malignant disease of the T-lymphocytes in the bone marrow, thymus, and/or blood. "These ExMVs enriched for NOTCH1-associated miRNAs alter the cell heterogeneity and the dynamics of T-cell leukemias." (PMID 38388648, 2024). "Our previous studies revealed that Notch1 is mutated in E2a-/- T cell leukemias and required for their survival." (PMID 35371057, 2022). "The median IC50 of the NOTCH1 mutant type cancer cell lines was smaller than that of the wild-type, indicating that an EGFR inhibitor (gefitinib) has potential therapeutic effects for T-cell leukemia with a NOTCH1 mutation." (PMID 33627666, 2021). "Transplantation of bone marrow expressing activated NOTCH1 alleles leads exclusively to T-cell leukemia development in the mouse." (PMID 24046360, 2013). "Gain-of-function mutations in the Notch1 gene are frequently found in several models of T cell lymphoma as well as in human T cell leukemias, including those resulted from loss of E protein function." (PMID 19688092, 2009). "In contrast to B-ALL, activating mutations of Notch1 are common in human T-cell leukemia." (PMID 31346528, 2019). "Activation mutations of Notch1 occurred relatively frequently in T-cell leukemia." (PMID 24312514, 2013). "The fusion gene STIL-TAL1 and mutations in BCL11B, NOTCH1, and USP7 have also been found and all been associated with the occurrence of T-cell leukemia." (PMID 38363891, 2024). "The fusion gene STIL-TAL1 and mutations in BCL11B, NOTCH1, and USP7 have been associated with T-cell leukemia." (PMID 38363891, 2024). "In our study, we took advantage of a mouse model of NOTCH1-induced T-cell leukemia that is strictly dependent on this oncogene and performed in vivo NOTCH1 inhibition using a gamma-secretase inhibitor." (PMID 32708470, 2020). "In murine T-cell leukemia models, MafB transcription factor enhances leukemogenesis of naturally occurring Notch1 mutants, by decreasing disease latency and/or increasing penetrance." (PMID 31346528, 2019). "Griffin and colleagues developed a human NOTCH1-induced T-cell leukemia zebrafish model, where the intracellular portion of NOTCH1 (ICN1) is express under the rag2 promoter." (PMID 28930163, 2017). "Given the many similarities between mouse and human metabolism, we took advantage of a mouse model of NOTCH1-induced T-cell leukemia to gain important insight into the metabolomics of T-ALL and to identify putative metabolite biomarkers useful for diagnosis and prognosis." (PMID 38928249, 2024). "USP7 cooperates with NOTCH1 to drive the oncogenic transcriptional program in T cell leukemia." (PMID 30898977, 2019). "Similarly, AMD3100 administration can prevent preleukemic BM infiltration in a Notch3-induced T-cell leukemia model or AMD3465 in Notch1-induced T-ALL." (PMID 31346528, 2019). "Recently, a study suggested that the activation of the Notch1 signaling pathway may contribute to adult T-cell leukemia and that Hes1 is upregulated in leukemic samples." (PMID 27681508, 2016). "It was shown that the induction of the T cell leukemia is dependent on the Notch1 signal strength." (PMID 25866806, 2015). "Furthermore, Notch1 is able to promote T cell leukemia-initiating activity by RUNX-mediated regulation of PKC-θ and reactive oxygen species." (PMID 24396472, 2014). "Moreover, expression of a constitutively active form of Notch1 in BM progenitors results in ectopic T cell development outside the thymus and T cell leukemia." (PMID 19688092, 2009). "Moreover, in T-ALL, MVs contain NOTCH1-dependent microRNAs, which control oncogenic pathways acting as autocrine stimuli and ultimately promote the expansion/survival of highly proliferative cell subsets of human T-cell leukemias." (PMID 38388648, 2024). "All these findings suggest that NOTCH1 dependent EV-miRs may sustain the growth/survival of immunophenotypically defined cell populations, altering the cell heterogeneity and the dynamics of T-cell leukemias in response to conventional therapies." (PMID 36550553, 2022).
T-cell leukemia (continued). "During T-cell transformation, high levels of activated Notch1 in murine T-cell progenitor models impair T-cell maturation, leading to the accumulation of CD4pos/CD8pos cells, promote thymic-independent T-cell development, and ultimately lead to T-cell leukemia." (PMID 32708470, 2020). "Interestingly, deletion of CCR7 in two models of B-cell leukemia failed to inhibit CNS infiltration, suggesting that CCR7 function may be specific for Notch1-induced T-cell leukemia." (PMID 28491865, 2017). "Furthermore, given the cell context-specificity of Notch target gene expression, it was important for us to use a T-ALL cell line in our study which has aimed to identify such relevant to T cell leukemia, even though Jurkat cells already express an overactive form of Notch1." (PMID 19508709, 2009). "Notable examples include NOTCH1, PHF6, and FBXW7, which are well-acknowledged for their role in T-cell leukemia, as well as BRAF, which was exclusively predicted in the hairy-cell group, in accordance with its recognized function as a marker for HCL." (PMID 38769532, 2024). "In T-cell leukemia, USP7 can regulate Notch1 at the transcriptional and post-translational levels and lead to increased expression of Notch1 target genes." (PMID 34179009, 2021). "Overall, our study supports previous researches indicating GSKJ4 as a promising therapeutic agent in Notch1- and TAL1- dependent T-ALL, while laying the basis for extending its potential use also to Notch3- and c-Myc- dependent T-cell leukemia contexts." (PMID 31001470, 2019).
breast tumor (34 papers, 2008 to 2025). "NOTCH1 mutations were identified exclusively in breast tumors, including one primary tumor, two recurrences, and one matched pair of primary/recurrent tumors." (PMID 36344544, 2022). "Notch1 is highly expressed in poorly differentiated breast tumors and associated with poor overall survival." (PMID 33413403, 2021). "Considering our primary objective, we found that NOTCH1 mRNA expression in breast tumour tissue follows a normal distribution in an unselected cohort of eBC patients with a median observation time of five years." (PMID 39153127, 2025). "The miR-106b-25 cluster through the direct repression of NEDD4L mediated breast tumor initiation by the activation of NOTCH1 signaling." (PMID 34809620, 2021). "NOTCH4 is an essential modulator of basal breast cancer stem cell (BCSCs) population, while NOTCH1 activity is more limited to luminal precursors both in the normal mammary gland as well as in breast tumors." (PMID 33822486, 2021). "These observed interactions between Pin1 and NOTCH1/4 is extremely relevant in modulating the NOTCH paralog‐driven functions in breast tumors." (PMID 33822486, 2021). "To further examine the relationship between autophagy and Notch1-IC, we examined the expression of Notch1-IC, Beclin1, and p62 in 31 freshly prepared human breast tumor specimens and matching normal breast tissue samples by western blotting." (PMID 27806347, 2016). "The negative correlation between Notch1-IC and Beclin1 and the positive correlation between Notch1-IC and p62 were observed in human breast tumor and its adjacent normal tissues." (PMID 27806347, 2016). "To explore the effects of autophagy-induced Notch1-IC degradation in cancer, we examined the correlation between Notch1-IC and autophagy in breast tumor." (PMID 27806347, 2016). "We found that Notch1 expression increased approximately 7-fold in breast tumor tissues (OR = 7.21; 95% CI, 4.7–11.7), indicating that Notch signaling is essential in breast tumorigenesis." (PMID 26121683, 2015). "Consistently, we found increased expression of the receptor Notch1 in human breast tumors as well as cell lines of the TNBC subtype." (PMID 26418877, 2015). "Our results demonstrate that the visfatin-Notch1 axis contributes to breast tumor growth through the activation of the NF-κB pathway." (PMID 24970818, 2014). "Visfatin and Notch1 were expressed at higher levels in breast tumors than in matched control tissues." (PMID 24970818, 2014). "In line with current knowledge, also in our cohort, the NOTCH1 mRNA expression is higher in breast tumour tissue than in normal breast tissue and is significantly associated with a more aggressive tumour biology (negative HR status, positive HER2 status and high uPA/PAI-1 status)." (PMID 39153127, 2025). "It was reported that NOTCH1 and JAG1 are highly expressed in poorly differentiated breast tumors and are associated with poor survival, whereas NOTCH2 expression has been correlated to high rates of disease-free survival, suggesting antagonistic functions of Notch1 and Notch2." (PMID 32796631, 2020). "Additionally, autophagy is inversely correlated with Notch1-IC expression and activation of Notch1 signaling in human breast tumors." (PMID 27806347, 2016). "In breast tumors, persistent Notch1 activity in tumor initiating or progenitor cells may have a negative impact on tumor progression." (PMID 25970777, 2015). "We propose that the expression profile of Notch1-expressing ERαneg cells could be relevant to identify important genes defining poorly differentiated basal-like breast tumors, believed to originate from ERαneg luminal progenitor cells." (PMID 25688859, 2015). "Breast tumors expressing high levels of NF-κB p65 exhibited increased expression of Notch1." (PMID 24970818, 2014). "Aberrant Notch signaling is involved in breast tumorigenesis: Notch-2 may act as a breast tumor suppressor, whereas Notch1, Notch-3, and Notch4 may act as breast oncogenes." (PMID 24970818, 2014).
breast tumor (continued). "Interestingly, Notch1 expression was positively associated with p65 expression, indicating a correlation between p65 and Notch1 in breast tumors." (PMID 24970818, 2014). "In contrast, Notch-1 levels dictated overall survival in basal breast tumors." (PMID 19025652, 2008). "We also analyzed whether NOTCH1 affects the growth and/or the onset of breast tumors." (PMID 23826634, 2013). "Its antiproliferative actions depends upon breast tumor subtype and distinct genetic characteristics (e.g., RARA amplification, NOTCH1 activating deletion)." (PMID 38360674, 2024). "In a further analysis of 4421 breast tumor patients, expression levels of CD73 correlated with the mRNA expression level of Notch1 (r = 0.40, p < 0.001)." (PMID 37391408, 2023). "Psoralidin, an active compound extracted from Psoralea corylifolia, targets NOTCH-1 in BCSCs and inhibits EMT and breast tumor growth." (PMID 36632469, 2023). "Like CD44KO cells, CD81 KO populations decreased protein levels of breast tumor-initiating markers including OCT4, NOTCH1, and phosphoSTAT3." (PMID 36193887, 2022). "Western blots detections also showed that 3,6-DHF administration significantly decreased the expression of Notch1 and NICD in xenograft breast tumors." (PMID 27345219, 2016). "NOTCH1 activity levels have also been shown to correlate with the development of resistance to conventional as well as to targeted therapies, leading us to hypothesize that NOTCH1 may contribute to therapeutic resistance and disease recurrence by regulating breast tumor-initiating cell activity." (PMID 22992387, 2012). "This may explain why Notch1 is preferentially up-regulated in some breast tumor models where it may expand tumor cells lacking expression of more terminal differentiation genes." (PMID 25970777, 2015).
atherosclerosis (32 papers, 2008 to 2026). A disease characterized by the build-up of fatty material and calcium deposition in the arterial wall resulting in partial or complete occlusion of the arterial lumen. "Accordingly, endothelial KLF11 deficiency in the diabetic atherosclerosis model increased the binding activities of lipoprotein particles and growth factors and the expression of Notch1 and Snai1." (PMID 39462409, 2024). "The reduction of endothelial Notch1 was identified as a predisposing factor for the onset of vascular inflammation and initiation of atherosclerosis." (PMID 37205094, 2023). "The reduction of NOTCH1 in ECs is a predisposing factor for vascular inflammation and atherosclerosis." (PMID 34447638, 2021). "Notch1 expression is increased under atheroprotective flow; Notch1 loss resulted in atherosclerosis in a mouse model of hypercholesterolemia." (PMID 33585446, 2020). "Overall, our findings point to the novel concepts that KRIT1 deficiency in ECs causes a redox-dependent downregulation of Notch1 activation and upregulation of proinflammatory endothelial CAMs, leading to a consequent increased susceptibility to ED and atherosclerosis." (PMID 31590384, 2019). "Furthermore, loss of Notch1 in adult endothelium increases hypercholesterolemia-induced atherosclerosis in the descending aorta." (PMID 29158473, 2017). "Finally, we also showed that NOTCH1 signaling regulates several pro-inflammatory genes associated with atherosclerosis." (PMID 29158473, 2017). "The use of Notch1 or VCAM1 blocking antibodies as well as the knockdown of endothelial Notch1 both reduced atherosclerosis progression after stroke." (PMID 40565303, 2025). "This interaction is particularly significant as NOTCH1 serves as a crucial protective factor against atherosclerosis." (PMID 40226530, 2025). "The homeostatic function of Notch1 has been demonstrated in animal models of atherosclerosis and pulmonary arterial hypertension." (PMID 40299408, 2025). "In macrophages isolated from patients with atherosclerosis, NOTCH1 appears to play a more prominent role than those of NOTCH2 and NOTCH3 in the regulation of the NF-κB signaling pathway and in the induction of pro-inflammatory gene expression." (PMID 35891967, 2022). "NOTCH1 is protective against disturbed flow-induced atherosclerosis, which is mediated through anti-inflammatory and anti–apoptotic effects." (PMID 35163238, 2022). "MiR-30c was associated with hyperlipidemia and atherosclerosis reduction in the Western diet-fed mice, while miR-126p limited atherosclerosis by suppressing Notch1 inhibitor delta-like-1 homolog in Mir126−/− mice." (PMID 34201137, 2021). "This work was later expanded to show that endothelial Notch1 was enhanced under atheroprotective flow profiles and removal of endothelial Notch1 resulted in increased atherosclerosis in a mouse model of hypercholesterolemia [8▪▪]." (PMID 29547401, 2018). "Notch1 selectively binds to Jagged1 under inflammatory conditions, and the Jagged1/Notch1 signaling pathway is then activated to promote angiogenesis in atherosclerosis." (PMID 30584451, 2018). "Here, Mack and colleagues identify a novel role for Notch1 as a mechanosensor in adult arteries, where it ensures junctional integrity through modulation of calcium signalling and limits atherosclerosis." (PMID 29158473, 2017). "To investigate the role of endothelial Notch1 in a pathophysiological setting, we utilized an atherosclerosis mouse model in which hypercholesterolemia was induced via PCSK9-AAV38." (PMID 29158473, 2017). "Our results further reveal that NOTCH1 is required to maintain junctional integrity, promote cell elongation in response to flow, and prevent atherosclerosis in the context of hypercholesterolemia." (PMID 29158473, 2017).
atherosclerosis (continued). "It has been proposed that Dll4 and Notch-1 are key regulators of macrophage activation in atherosclerosis." (PMID 27973542, 2016). "MiR126 has also been shown to prevent atherosclerosis formation by promoting endothelial cell proliferation and turnover, through the suppression of the Notch1 inhibitor delta-like 1 homolog (Dlk1)." (PMID 26331273, 2015). "Recently, cyclic strain was shown to up-regulate Notch1 in human vascular EC and this process was responsible for significantly increased tube-formation in matrigel suggesting a role in development of atherosclerosis." (PMID 18764931, 2008). "However, there are also reports showing that blockade of Notch1 reduces cytokine-induced endothelial inflammation and that endothelial Notch1 knockout leads to the suppression of atherosclerosis." (PMID 40299408, 2025). "Among them, hsa-miR-181b-5p was found to be negatively correlated with occlusion size, and previous studies demonstrated that miR-181b exerts a protective effect against atherosclerosis by inhibiting endothelial dysfunction and inflammation by targeting Notch1." (PMID 35329950, 2022). "As discussed in previous paragraphs, the first step of atherosclerosis involves the interplay between the endothelium and infiltrating immune cells, step in which Notch1 in particular plays a crucial role by preventing the expression of adhesion molecules on ECs." (PMID 31191522, 2019). "In summary, the combination of TMP and PF suppresses ox-LDL-induced angiogenesis in HUVECs by inhibiting both the VEGF/VEGFR2 and the Jagged1/Notch1 signaling pathways, which might contribute to the stability of plaques in atherosclerosis." (PMID 30584451, 2018). "Similarly, in macrophages and monocytes, miR-146a targets tumor necrosis factor receptor–associated factor 6 (TRAF6), leading to inhibition of NF-κB-driven inflammation and atherosclerosis, and promotes macrophage polarization toward an anti-inflammatory phenotype by inhibiting Notch1." (PMID 34527667, 2021). "Taking together their specificity and potential for reduced systemic toxicity, it is hoped that this localized treatment of stenosed vessels with Notch1 specific siRNA, could represent a novel therapy for either restenosis which may accompany vein grafting, post angioplasty or atherosclerosis." (PMID 24416200, 2014). "Consistently, endothelial Notch1 has also been demonstrated to be suppressed by inflammatory lipids, resulting in increased monocyte adhesion and more severe HFD induced atherosclerosis." (PMID 38733496, 2024). "Recent studies found that NOTCH1 is activated by HSS in adult arteries, and this pathway is a key regulator of adherens junctions and vascular permeability and protects arteries from atherosclerosis." (PMID 36044575, 2022). "Considering no direct evidence connecting CD38, PTPN11, NOTCH1, TLR7, and KAT2B with the pathogenesis of MMD, their roles in atherosclerosis may also provide a new perspective and direction for future research on the molecular targeted therapy of MMD." (PMID 36605987, 2022). "Thus, while our studies identify a non-canonical Notch1 pathway that can be activated by CTSL in a ligand-independent fashion to induce senescence, our findings also reveal a role of senescence in the development of atherosclerosis." (PMID 42210653, 2026).